FOXA1 (forkhead box A1)
Diseases named in the same sentence as FOXA1 in open-access papers (continued):
Sharing a sentence is not in itself a finding about the gene and the disease.
prostate carcinoma (continued). "Moreover, in vivo studies and a clinical samples investigation have shown that FOXA1 facilitates prostate cancer angiogenesis." (PMID 35627227, 2022). "The mutual exclusivity of FOXA1 and FOXA2 mutations in prostate cancer and EC might seem counterintuitive given that they share diverse embryonic functions and broad expression across the endoderm and its derivatives." (PMID 35703180, 2022). "In addition, FOXA1 activity in prostate cancer can be modulated post-translationally through various mechanisms such as LSD1-mediated protein demethylation." (PMID 32946061, 2021). "The expression of FOXA1 was observed to cooperate and imbalance the AR cistrome in regulating AR signaling in prostate cancer cells, which may form a mechanism compensating for the functional defects of AR, even in PBMCs with a low abundance of AR expression." (PMID 34867780, 2021). "The ability of FOXA1 mutants to activate EMT may play a role in prostate cancer metastasis and progression in certain types such as NEPC." (PMID 32946061, 2021). "We know that FOXA1 has been reported to help shape AR signaling and drives growth and survival of prostate cancer cells, Which may be a potential explanation for the differences in prognosis among White, Black, and Asian PCa patients." (PMID 34148031, 2021). "Accordingly, recent findings point towards the significant impact of FOXA1 in modulating nuclear steroid receptor activity in breast and prostate cancer, suggesting that FOXA1 may significantly contribute to pro-tumorigenic phenotype." (PMID 36046086, 2021). "FOXA1 has been proved as a driver of prostate cancer onset and progression." (PMID 34445492, 2021). "Recent functional characterization of FOXA1 mutants shed light on their complex modes of action in driving prostate cancer where the function may be divergent depending on the residues affected." (PMID 32946061, 2021). "Three recurrent structural variants map to prostate cancer genes SH2B3, ATP10A and FOXA1." (PMID 34090332, 2021). "FOXA1 mutants can remodel the accessible chromatin landscapes of prostate cancer." (PMID 32946061, 2021). "An example is the new finding that LSD1 regulates FOXA1 activity which implies the use of LSD1 inhibitors may be a viable approach to antagonize FOXA1 activity in prostate cancer." (PMID 32946061, 2021). "Furthermore, the expression of FOXA1 is related to tumorigenesis and the progression of prostate cancer." (PMID 33632199, 2021). "Our data suggest that BRG1 binding is associated with the expression of DNA replication genes in prostate cancer cells that is independent of AR and FOXA1." (PMID 33596994, 2021). "Gaining insight on the cis-regulatory plexuses of important genes such as FOXA1 in prostate cancer may provide new avenues to inhibit other drivers across various cancer types to halt disease progression." (PMID 31974375, 2020). "A study of a cohort of 333 primary prostate carcinomas showed that 74% of these tumors fell into one of seven subtypes of a molecular taxonomy defined by specific gene fusions (ERG,ETV1/4 and FLI1) or mutations (SPOP,FOXA1 and IDH1)." (PMID 33058520, 2020). "FOXA1 is a driver factor in the incidence and progression of prostate cancer." (PMID 35134148, 2020). "Moreover, overexpression of FOXA1 was also found in metastatic and castration-resistance prostate cancer that correlated with higher pT stage and Gleason score." (PMID 32655839, 2020). "Studies in prostate cancer, thyroid cancer, and glioma have shown that FOXA1 is highly expressed in tumor tissues, has a significant correlation with tumor grade, invasion, and metastasis and poor prognosis of patients, and plays a role in promoting tumorigenesis and development." (PMID 32411194, 2020). "However, despite all the evidence on the oncogenic role of FOXA1 in prostate cancer there are also reports that reveal its role as a suppressor of EMT." (PMID 32655839, 2020).
prostate carcinoma (continued). "Interestingly, a significant fraction of breast cancer risk SNPs have been found to alter the affinity of chromatin for pioneer factor FOXA1 with which HOXB13 interacts in prostate cancer cells." (PMID 32546843, 2020). "Based on genomic profiles, prostate cancer can be divided into seven molecular subtypes which bear distinct oncogenic drivers including fusions with ETS family members (ERG, ETV1, ETV4, and FLI1) and mutations in SPOP, FOXA1, and IDH1." (PMID 33273988, 2020). "An earlier study of a cohort of 333 primary prostate carcinomas showed that 74% of these tumors fell into one of seven subtypes of a molecular taxonomy defined by specific gene fusions (ERG, ETV1/4 and FLI1) or mutations (SPOP, FOXA1 and IDH1)." (PMID 33058520, 2020). "Hence, FOXA1 contributes to AR-dependent and AR-independent processes favouring prostate cancer development." (PMID 31974375, 2020). "Therefore, FoxA1 functions to guide androgen receptor binding to the genomic sites in prostate cancer cells." (PMID 31552182, 2019). "Forkhead box protein A1 (FOXA1) modulates the transactivation of steroid hormone receptors and thus may influences tumor growth and hormone responsiveness in prostate cancer." (PMID 31888619, 2019). "SNP located in ARE, as well as in FOXA1 and ERG binding sites in Human were enriched in prostate cancer susceptibility loci, whereas MEHP may advance the progression of prostate cancer through activating the hedgehog pathway." (PMID 31181066, 2019). "Interestingly, at the reprogrammed AR binding sites in human prostate cancer cells it was reported the colocalized binding of FOXA1 and HOXB13—two prostate master transcription factors." (PMID 31366128, 2019). "FoxA1 also has androgen receptor-independent function in prostate cancer." (PMID 31552182, 2019). "In addition to these genetic alterations, FOXA1 is downregulated in CRPC as compared with primary prostate cancer, suggesting a tumor suppressor role." (PMID 31366128, 2019). "On the contrary, prostate-cancer-specific enhancers had motifs for FOXA1, GRHL2, AR, and ETS." (PMID 31515496, 2019). "Another recent study suggests that AR variants are dependent on FOXA1 for sustaining a pro-proliferative gene signatures and agents targeting FOXA1 may represent novel therapeutic options for patients with castrate-resistant prostatic cancer." (PMID 29581876, 2018). "FOXA1, as a nuclear receptor regulatory factor, is not limited to ERα as it also interacts with the androgen receptor (AR) to regulate its deposition to chromatin in prostate cancer cells." (PMID 30139998, 2018). "In addition to recurrent FOXA1 forkhead domain mutations, the 14q21.1 region is also a recurrent partner in ETV1-activating structural rearrangements in prostate cancer." (PMID 30272002, 2018). "This suggests that FOXA1 3′-UTR mutations are not simply a late or predominantly subclonal event in prostate cancer." (PMID 30272002, 2018). "FOXA1 expression is lineage restricted, and very high in prostate cancer." (PMID 30272002, 2018). "These properties confer the ability of FOXA1 to act as a pioneer factor for both estrogen receptor α and androgen receptor, controlling their binding, location, and function in breast and prostate cancer respectively." (PMID 30572598, 2018). "In addition, aberrant activation of a gastrointestinal differentiation program in prostate cancer, which can mediate castration resistance, is driven by HNF4γ in cooperation with FoxA1." (PMID 30475207, 2018). "Accordingly, prostate cancer exhibits higher FOXA1 expression than other malignancies." (PMID 30272002, 2018). "The best-known pioneering factor for its role in prostate cancer is FOXA1." (PMID 29888169, 2018).
prostate carcinoma (continued). "In estrogen receptor-positive breast cancer, prostate cancer, acute myeloid leukemia, and thyroid carcinoma, FOXA1 exhibits a potential cancer-promoting effect; however, it causes tumor inhibition in estrogen receptor-negative breast cancer, advanced prostate cancer, and pancreatic cancer." (PMID 29208003, 2017). "Increasing FOXA1 activity causes indiscriminate opening of closed chromatin, attracting the AR to ARE half sites at the expense of genes with canonical ARE that promote prostate cancer progression." (PMID 28264478, 2017). "This pioneer function is of particular importance in gene expression of endocrine-related cancers, including breast and prostate cancers as FoxA1 is a key cooperating factor for the nuclear hormone receptors, estrogen receptor-α (ER), and androgen receptor (AR)." (PMID 25401090, 2014). "Thus, FOXA1 expression is considered a predictor of poor survival in prostate cancer and triple-negative breast cancer." (PMID 24512546, 2014). "In endometrial cancer, FOXA1 is important for inhibition of cell proliferation and migration, and in prostate cancer cell lines FOXA1 was recently shown to inhibit cell motility and epithelial to mesenchymal transition (EMT) through regulation of the transcription factor SLUG." (PMID 24849812, 2014). "By contrast, in prostate cancer, the effect of FOXA1 on AR binding is more complex." (PMID 23192763, 2013). "The forkhead protein, FOXA1, is a critical interacting partner of the nuclear hormone receptors, oestrogen receptor-α (ER) and androgen receptor (AR), which are major drivers of the two most common cancers, namely breast and prostate cancer." (PMID 23420418, 2013). "Moreover, FOXA1 expression levels have opposing effects on patient outcome in breast and prostate cancer." (PMID 23420418, 2013). "Conversely, in prostate cancer, high levels of FOXA1 correlate with poor prognosis." (PMID 23420418, 2013). "FOXA1 is involved in cell-cell signaling, and it promotes tumor progression in prostate cancer." (PMID 24564989, 2013). "Interestingly, there is evidence of a common reliance in late stage disease as FOXA1 levels are high in both breast and prostate cancer metastases." (PMID 23420418, 2013). "An analogous case in prostate cancer is the altered target gene spectrum of the androgen receptor caused by changes in the expression of interacting transcription factors like HOXB13 and FOXA1." (PMID 24213107, 2011). "FoxA1 and FoxA2 are important regulators of epithelial proliferation and differentiation during prostate development that exhibit altered patterns of expression in human prostate cancer." (PMID 17343742, 2007). "Therefore, a reliable framework to detect and characterize FOXA1 alterations may improve outcomes for patients with advanced prostate cancer." (PMID 39745364, 2025). "However, whether FOXA1 plays a broader or context-dependent role in regulating hypoxia pathways in prostate cancer remains poorly understood." (PMID 40643528, 2025). "Prostate cancer exhibits even more pronounced racial variations: Black men show higher frequencies of SPOP and ZFHX3 mutations but lower rates of TMPRSS2‐ERG fusions and PTEN deletions compared to White men, while Asian men demonstrate increased FOXA1 mutations and fewer PTEN alterations." (PMID 41187942, 2025). "Our initial observation that global PHD inhibition using DMOG led to HIF1α stabilization but paradoxically reduced FOXA1 protein levels prompted us to investigate whether individual PHD isoforms differentially regulate FOXA1 expression in prostate cancer cells." (PMID 40643528, 2025). "Thus, GR could have both indirect and direct crosstalk relationships with E2F1 in NEPC, like the interaction between FOXA1 and GR in AR-positive prostate cancer cells." (PMID 39027480, 2024).
prostate carcinoma (continued). "Additionally, our Co-IP results further confirm FOXA1’s binding with AR in prostate cancer." (PMID 39097593, 2024). "Interestingly, previous studies have shown that GATA2 and FOXA1 co-occupy 55% of all hormone-responsive AR binding sites in the LNCaP prostate cancer cell line, suggesting a potential cooperative mechanism between these two pioneer transcription factors in regulating the AR cistrome." (PMID 36212399, 2022). "The importance of FOXA1 regulation of prostatic and non-prostatic AR-chromatin targeting is well implicated through several studies and also reported as the third most frequently mutated gene in prostate cancer." (PMID 36046086, 2021). "Indeed, FOXA1 has been hypothesized to be a mediator of hormonal response in breast and prostate cancer, and a hormonal regulatory complex involving FOXA1, GATA2 and AR has been shown to control gene expression in prostate cancer." (PMID 32850701, 2020). "However, it is unclear the precise contribution of FOXA1 alterations in prostate cancer development since this transcription factor may exert both tumor-suppressive and oncogenic roles." (PMID 31366128, 2019). "The connection between FOXA1 coding region and UTR mutations, together with the unusually high rate of non-frameshift indels in the FOXA1 forkhead domain, suggests that prostate cancer driver mutations in this domain arise due to a combination of a localized mutation process and clonal selection." (PMID 30272002, 2018). "FOXA1's inhibitory effect on SEMA3C expression may also be of significance given that FOXA1, which is often found to be mutated in advanced PCa, may account for elevated SEMA3C expression in advanced prostate cancer." (PMID 28038451, 2017). "Likewise, SNAIL2/SLUG directly represses the FOXA1 promoter in prostate cancer cells." (PMID 29155818, 2017). "In an analysis of 333 individual prostate cancer exomes, TCGA identified seven subtypes defined either by gene fusions involving the ETS family (59% of cases), specifically ERG, ETV1, ETV4, or FLI1, or recurrent mutations (15% of cases) in SPOP, FOXA1, or IDH1." (PMID 28423598, 2017). "However, the ability of FOXA1 expression to predict risk of BCR in the specific patient population of men undergoing SRT for recurrent prostate cancer after RP has not been assessed to date." (PMID 26986977, 2016). "No binding sites were found at the TSS of these genes in the human breast adenocarcinoma cell line MCF7 or in the human prostate adenocarcinoma cell line LNCaP, suggesting that the regulatory role of FOXA1 in breast and prostate cancer might differ from that of lung and liver cancer." (PMID 24093963, 2013). "On the contrary, in prostate cancer, as AR is still able to bind in the absence of FOXA1, a mutation in FOXA1 which inhibits its DNA binding capacity may not inhibit AR binding, but could instead alter its binding profile and transcriptional targets." (PMID 23420418, 2013). "In prostate cancer cell lines, several AR regulators have been identified, including GATA2, HOXB13, FOXA1, and TFAP2C." (PMID 41596366, 2026). "Several markers (FOXA1 and RASSF1A) were methylated in both lung cancer and PCa, while SEPT9 and SOX17 were hypermethylated across lung, colorectal, and prostate cancers." (PMID 41008642, 2025). "FOXA1 is the archetypal PF6,32, and its functional role as the adaptor between chromatin and NR transcription factors in breast and prostate cancer is well-established." (PMID 41168397, 2025). "FOXA1 and FOXA2, members of this family, are known to interact with AR to regulate transcriptional programs in prostate cancer." (PMID 40898340, 2025).
prostate carcinoma (continued). "Prostate cancer studies revealed that LSD1, along with BRD4 and FOXA1, formed a network enriched in the super enhancer region to regulate MYC expression and influence tumor development." (PMID 39838405, 2025). "This reciprocal relationship was similarly observed in two additional prostate cancer cell lines, PC3 and DU145, indicating that HIF1α-mediated suppression of FOXA1 is a broadly conserved response." (PMID 40643528, 2025). "To delineate isoform-specific functions of PHDs in FOXA1 regulation, we employed lentiviral shRNA-mediated silencing of PHD1, PHD2, and PHD3 in V16A prostate cancer cells." (PMID 40643528, 2025). "This section also analyzed the expression of FOXA1 and SLC7A11 across different prostate cancer cell lines." (PMID 41330917, 2025). "The selective effects of PHD1 depletion on both FOXA1 protein levels and KLK3 transcription underscore its unique and functionally relevant role in modulating androgen receptor signaling pathways in prostate cancer." (PMID 40643528, 2025). "Prostate cancer cells rely on AR, HOXB13 and FOXA1-regulated transcriptional programs for tumor progression and resistance to anti-androgens." (PMID 38730575, 2024). "We also observed strong inhibition of other prostate cancer oncogenic signaling, including ERG and FOXA1, after CBPD-409 treatment." (PMID 38586029, 2024). "FOXA1, a gene family that includes FOXO1, promotes cell proliferation and inhibits cell motility and EMT in prostate cancer cells." (PMID 38571514, 2024). "We further showed that degradation of these subunits, along with PBRM1, led to rapid and widespread chromatin compaction, perturbing essential oncogenic programs driven by transcription factors such as AR, FOXA1, and ERG in prostate cancer models." (PMID 38557192, 2024). "Subsequent analysis revealed that only FOXA1, a potential regulator of PUS1, was significantly upregulated in prostate cancer tissues." (PMID 39247811, 2024). "A small molecule inhibitor of NR2F2 was recently shown to reduce prostate cancer tumor growth, specifically by interrupting the interaction of NR2F2 with FOXA1, a master regulator in prostate tumorigenesis." (PMID 39171293, 2024). "Then, we also showed that FOXA1 was positively correlated with FBW7 expression in liver cancer, prostate cancer and bladder cancer by using the GEPIA web tool." (PMID 35081978, 2022). "Together, these data show that SWI/SNF ATPase inactivation specifically leads to genome-wide collapse of the AR, FOXA1, ERG and MYC-activated core enhancer circuitry in prostate cancer cells." (PMID 34937944, 2022). "In the following review, we will discuss the transcription factors FOXA1, HOXB13, GATA2, ERG, and MYC as they relate to the AR cistrome and its transcriptional output during prostate cancer evolution." (PMID 36212399, 2022). "FOXA1 is driven by the androgen receptors and regulates the expression of TMPRSS2 and ACE2 in prostate cancer cells." (PMID 35458567, 2022). "TBX3 and NFIC, two nuclear factors that are amplified or overexpressed in mCRPC, were vulnerabilities in other prostate cancer models, including ones that were ART resistant, and bound to FOXA1 transcription regulatory elements." (PMID 35550030, 2022). "Fortunately, cancer driver genes in prostate cancer, ERG, ETV1, ETV4, SPOP, and FOXA1, have been identified and their roles have been proved through basic and clinical research." (PMID 36579559, 2022).